MSL2 (MSL complex subunit 2)
Description:
Non-catalytic component of the MSL histone acetyltransferase complex, a multiprotein complex that mediates the majority of histone H4 acetylation at 'Lys-16' (H4K16ac), an epigenetic mark that prevents chromatin compaction. The MSL complex is required for chromosome stability and genome integrity by maintaining homeostatic levels of H4K16ac. The MSL complex is also involved in gene dosage by promoting up-regulation of genes expressed by the X chromosome (By similarity). X up-regulation is required to compensate for autosomal biallelic expression (By similarity). The MSL complex also participates in gene dosage compensation by promoting expression of Tsix non-coding RNA (By similarity). MSL2 plays a key role in gene dosage by ensuring biallelic expression of a subset of dosage-sensitive genes, including many haploinsufficient genes (By similarity). Acts by promoting promoter-enhancer contacts, thereby preventing DNA methylation of one allele and creating a methylation-free environment for methylation-sensitive transcription factors such as SP1, KANSL1 and KANSL3 (By similarity). Also acts as an E3 ubiquitin ligase that promotes monoubiquitination of histone H2B at 'Lys-35' (H2BK34Ub), but not that of H2A. This activity is greatly enhanced by heterodimerization with MSL1. H2B ubiquitination in turn stimulates histone H3 methylation at 'Lys-4' (H3K4me) and 'Lys-79' (H3K79me) and leads to gene activation, including that of HOXA9 and MEIS1.
Synonyms: MSL-2; KIAA1585; MSL2L1; RNF184; FLJ10546; KBHS
Tractability: PROTAC: UniProt records ubiquitination sites on it; ubiquitination databases record sites on it; its protein half-life has been measured.
Gene: Protein-coding gene on chromosome 3 (136,148,917 to 136,197,241, reverse strand). Ensembl gene ENSG00000174579.
Subcellular location: Nucleus; Chromosome
Subcellular location (Human Protein Atlas): Cytosol; Nucleoplasm
Pathways (Reactome):
Chromatin organization: HATs acetylate histones
Gene Ontology:
Molecular function: histone H2B ubiquitin ligase activity; protein binding; ubiquitin protein ligase activity; chromatin-protein adaptor activity; promoter-enhancer loop anchoring activity
Biological process: DNA damage response; protein monoubiquitination; epigenetic regulation of gene expression; protein localization to chromatin; protein ubiquitination; positive regulation of DNA-templated transcription
Cellular component: chromatin; chromosome; MSL complex; nucleus; nucleoplasm
Genetic constraint (gnomAD): Loss-of-function variants: 2 observed, 37.35 expected, observed/expected ratio (o/e) 0.0535, 90% interval 0.021 to 0.17. The upper end of that interval is the gene's LOEUF score, 0.17, which puts it in group 1 of 6, group 1 being the genes least tolerant of losing a copy. Missense variants: 518 observed, 741.99 expected, observed/expected ratio (o/e) 0.7, 90% interval 0.65 to 0.75. Synonymous variants: 291 observed, 270.27 expected, observed/expected ratio (o/e) 1.08, 90% interval 0.98 to 1.19.
Homologues: Orthologues: chimpanzee MSL2 (100% identical), macaque MSL2 (100% identical), guinea pig MSL2 (99% identical), rabbit MSL2 (99% identical), pig MSL2 (99% identical), dog MSL2 (99% identical), mouse Msl2 (99% identical), rat Msl2 (92% identical), tropical clawed frog msl2 (72% identical), zebrafish msl2b (61% identical), zebrafish msl2a (46% identical), Drosophila melanogaster msl-2 (23% identical).
Diseases named in the same sentence as MSL2 in open-access papers:
MSL2 is named in the same sentence as 10 diseases in open-access papers, as found by Europe PMC text mining. Sharing a sentence is not in itself a finding about the gene and the disease. The quoted sentences say what the papers report.
hepatocellular carcinoma (4 papers, 2021 to 2024). A malignant tumor that arises from hepatocytes. "Our group has reported that MSL2 and HULC maintain HBV cccDNA minichromosome stability through the degradation of APOBEC3B in hepatoma cells." (PMID 34931766, 2021). "Our group has reported that HBx-elevated MSL2 regulates the HBV cccDNA minichromosome in hepatoma cells, thus promoting the development of HCC and forming a positive feedback loop of HBx/MSL2/cccDNA/HBV55." (PMID 34931766, 2021).
autism (2 papers, 2021 to 2025). Persistent deficits in social interaction and communication and interaction as well as a markedly restricted repertoire of activity and interest as well as repetitive patterns of behavior. "Finally, pathogenic variants in MSL2 lead to Karayol–Borroto–Haghshenas neurodevelopmental syndrome (MIM 620985), associated with developmental delay, intellectual disability, gait disturbance, dysmorphism, and autism." (PMID 41438488, 2025).
liver cancer (2 papers, 2022 to 2024). An epithelial or non-epithelial malignant neoplasm that arises from the liver. "Additionally, HBx upregulates MSL2 by activating YAP/FoxA1 signaling, and HBx-elevated MSL2 modulates HBV cccDNA in liver cancer cells, leading to hepatocarcinogenesis." (PMID 35784274, 2022).
chronic renal failure (1 paper, 2018). "Such regulation also matters in mammals, e.g., for the MSL2 targets Six1-4 or Sall1, whose haploinsufficiency causes syndromes associated with hearing loss, chronic renal failure, limb, and ear anomalies in humans." (PMID 30194291, 2018).
sterility (1 paper, 2021). "Germ line–specific loss of msl-2 results in sterility that is accompanied by severe atrophy of germline tissue." (PMID 34266874, 2021).
tumor (4 papers, 2022 to 2024). "The male-specific lethal 2 homolog (MSL 2) gene suppresses tumor proliferation through disruption-induced excessive chromosomal instability (CIN)." (PMID 39376611, 2024). "Additionally, miRNA-296-3p could inhibit HCC cell proliferation and invasion targeting MSL2 and functions as a tumor suppressor (Li, An & Gao, 2021)." (PMID 37426414, 2023).
neurodevelopmental disorder (1 paper, 2024). A behavioral and cognitive disorder with onset during the developmental period that involves impaired or aberrant development of intellectual, motor, or social functions. "Taken together, our descriptions of dysmorphic face and other features support the causal role of MSL2 in a likely syndromic neurodevelopmental disorder and add MSL2 to a growing list of epigenetic genes implicated in ASD." (PMID 38702431, 2024).
MSL2 also shares sentences with these, for which no sentence is quoted: developmental delay (1 paper); Intellectual disability (1); Ventriculomegaly (1).